RHOA (ras homolog family member A)
Diseases named in the same sentence as RHOA in open-access papers (continued):
Sharing a sentence is not in itself a finding about the gene and the disease.
cervical carcinoma (continued). "Previous studies have shown that the expression of RhoA, ROCK-1, and ROCK-2 is significantly elevated in cervical cancer cells." (PMID 40655948, 2025). "And through the correlation analysis of the expressions of ECT2 and RHOA, ROCK1, and ROCK2 in cervical cancer samples in TCGA database, it was found that the expression of ECT2 was significantly positively correlated with RhoA, ROCK1, and ROCK2." (PMID 40655948, 2025). "Cervical cancer metastasis is promoted by VEGF-C upregulating and activating moesin protein through RhoA/ROCK-2 pathway." (PMID 32443784, 2020). "Therefore, in the present study, the targeting relationship between miRNA-200b and RhoA protein was verified, and its role and possible mechanism of action in cervical cancer cell proliferation and apoptosis were investigated, providing a new target for the treatment of clinical cervical cancer." (PMID 33336057, 2020). "Metformin displays antimigration effects in cervical cancer cells by inhibiting filopodia and lamellipodia formation through the suppression of FAK, Akt and its downstream Rac1 and RhoA protein." (PMID 31870092, 2019). "Several genes involved in pathways altered in early stages of cervical cancer, such as CASP9 and EGR2 involved in apoptosis and MYC-N, CCNA and RhoA involved in cell proliferation, were altered by HPV16 E2 expression." (PMID 21599968, 2011). "Interestingly, the LIR motif is also present in both the RhoA and RhoB proteins, and their levels were modestly increased by RAB33A overexpression in cervical cancer cells." (PMID 40000633, 2025). "HeLa cells of cervical cancer were divided into five groups: blank control group, negative control group (miRNA-200b mimic NC), miRNA-200b mimic group, RhoA-negative control group, and RhoA overexpression group." (PMID 33336057, 2020). "In vitro studies have shown that morphine can promote the proliferation of cervical cancer cells by activating the opioid receptor-dependent EGFR-mediated signaling pathway and stimulate migration by activating the opioid receptor-independent RhoA-mediated signaling pathway." (PMID 40129947, 2025). "We have previously shown colocalization of ezrin in adherens junctions with N-Cadherin but no expression of E-Cadherin in HPV 18 containing HeLa cervical carcinoma cells, as well as the requirement for Rac1, phosphatidylinositol-4-phosphate 5-kinase (PIPKα) and RhoA for this localization." (PMID 21747943, 2011).
breast tumor (28 papers, 2002 to 2025). "In PR+ breast tumors, greater red meat consumed (βadj. = 0.305, p = 0.002) and high ratio of TP:DF (βadj. = 0.229, p = 0.034) were associated with higher fold changes of RhoA expression." (PMID 31333806, 2019). "RhoA, RhoB, Rac1/Rac1b, and Cdc42 are overexpressed in breast tumors, with RhoA expression associated with advanced stages of the disease." (PMID 19703301, 2009). "In summary, findings could suggest the binary settings of pro-metastatic genes, including CTTN-ROCK and RhoA-ROCK in association with a breast tumor diagnosed with infiltration into axillary lymph nodes which is representative of local breast metastasis." (PMID 33407452, 2021). "Indeed, in SKBR3 breast tumor cells, it was recently shown that Memo controls the association of RhoA and its effector mDia with the plasma membrane in response to ErbB2 activation, thereby impacting on recruitment of actin-binding proteins, MT dynamics and migration." (PMID 22412880, 2012). "In breast tumor cells, cerivastatin exerts its anticancer effects by inhibiting RhoA prenylation, thereby suppressing the RhoA/ROCK pathway and inducing cytoskeletal destabilization, which leads to a loss of traction forces essential for cell migration." (PMID 41211420, 2025). "Collectively, these observations established a physiologically relevant correlation between RKIP/RhoA expression and membrane E-cadherin expression and localization, and the metastatic potential of 4T1 primary breast tumors." (PMID 34465801, 2021). "In a separate study utilizing a FRET (Fluorescence resonance energy transfer) reporter that can allow for real-time quantification of RhoA, enhanced RhoA activity was found in the invasive PyMT-induced breast tumors relative to control tumors." (PMID 32992837, 2020). "Using expression data extracted from the TCGA project "Breast Invasive Carcinoma", we confirmed significant increase of the RhoA/RhoB expression ratio in triple negative breast tumors compared to other breast tumors (p<0.001)." (PMID 33162807, 2020). "RhoA, Rac1, and Cdc42 are overexpressed in human breast tumors and are all essential for cell migration, indicating that the migratory phenotype we observed in Cx43-shRNA S1 cells is triggered downstream of Rho GTPase signaling." (PMID 30857262, 2019). "The initial evidence for Rho GTPases in breast tumor invasion and metastasis in vivo came from studies expressing dominant negative forms of RhoA, RAC1 and Cdc42." (PMID 27902969, 2017). "Aberrantly high expression of RhoA is thought to be a trigger of breast tumor proliferation and metastasis." (PMID 27713154, 2016). "Downregulation of c-Src/Twist or inhibition of miR-10b production results in HOXD10 upregulation and causes a decrease in the expression of RhoA/RhoC and a reduction of ROK-mediated breast tumor cell invasion." (PMID 27070574, 2016). "Similar to the ERM protein family (i.e., ezrin and moesin), RhoA, RhoB and Cdc42 immunoreactivity was also observed in the stromal compartment of the breast tumour samples and its blood vessels." (PMID 23420497, 2013). "Rho family GTPases are greatly overexpressed in breast tumours and RhoA is necessary for Ras-mediated transformation and metastatic spread." (PMID 15535843, 2004). "It is well-established that RhoA overexpressed in breast tumors." (PMID 31333806, 2019). "CD44 is known to stimulate breast tumor cell invasion through the RhoA pathway." (PMID 25840418, 2015). "RhoA is highly upregulated in breast tumors but barely detectable in normal adjacent tissues." (PMID 24158494, 2014). "Moreover, in vitro assays indicate that inhibition of ICMT-mediated methylation results in decreased motility of breast tumor cells by reducing the GTP-bound RhoA and Rac1." (PMID 25361001, 2014). "Similarly, previous studies have reported that activated RhoA is critical for breast tumor invasion and metastasis." (PMID 22655072, 2012).
breast tumor (continued). "We propose that in these breast tumour cells this reciprocal antagonism between RhoA and Rac1 precisely coordinates the specificity and/or magnitude of the pathophysiological response of NHE1 to serum deprivation, with concomitant increases in motility and invasion and hence malignant progression." (PMID 15535843, 2004). "The hyaluronan/CD44 signaling was also correlated to the activation of RhoA/ROCK pathway and subsequent the phosphorylation of NHE-1, leading to breast tumor cell invasion." (PMID 33407452, 2021). "These events lead to the reduction of the tumor suppressor protein, HOXD10, RhoA/RhoC overexpression, ROK activation, and breast tumor cell invasion." (PMID 27070574, 2016). "Activation of RhoA results in release of megakaryoblastic leukemia 1 (MKL1), which in turn has been observed to alter the transcriptional activity of ERα, known to play a critical role in breast tumors." (PMID 37559094, 2023). "For breast tumours we found that there was only a tendency in the expression of rhoB, rhoC and rac1 mRNA, but not of rhoA mRNA, to increase with grading." (PMID 12237774, 2002). "In contrast, analyzing RHOA expression in primary GBM and breast tumors, using the same TCGA cohorts, showed no significant RHOA expression for tumors with PTEN splice variants." (PMID 34680293, 2021).
Stroke (28 papers, 2013 to 2025). Sudden impairment of blood flow to a part of the brain due to occlusion or rupture of an artery to the brain. "The RhoA/ROCK pathway is implicated in the pathophysiology of central nervous system (CNS) diseases such as stroke, optic nerve injury, spinal cord injury (SCI), and neurodegenerative diseases." (PMID 32724667, 2020). "Our results suggest that targeting excessive TRPV4 and RhoA pathway activity may hold therapeutic promise for patients with TRPV4 mutations and in other conditions associated with TRPV4 and RhoA dysregulation, such as traumatic brain injury, stroke, and pulmonary edema." (PMID 33664271, 2021). "For example, search terms included “stroke OR cerebral ischemia AND RhoA/ROCK”, “MSC OR EVs OR secretome AND stroke”, and “mTOR AND stroke OR cerebral ischemia AND treatment”." (PMID 38666949, 2024). "It is possible that increased RhoA/ROCK signaling in platelets in Rock2+/− females activates thrombus formation during PT stroke induction, resulting in faster vessel occlusion and therefore decreased CBF in these mice." (PMID 38164600, 2024). "Valsartan, an angiotensin II type 1 receptor (AT1) antagonist, but not prazosin, an α 1-adrenergic receptor antagonist, decreased the active form of RhoA in VSMC from stroke-prone SHRs." (PMID 34357074, 2021). "Rho kinase activity is upregulated in endothelial cells after stroke, and RhoA/Rho-kinase inhibition was shown to alleviate Aβ42-induced BBB disruption." (PMID 33260683, 2020). "In the previous studies of ONC and stroke, researchers found that inhibition of the RhoA/ROCK pathway had neuroprotective effects." (PMID 32724667, 2020). "In conclusion, we provide the first evidence that EA enhances rehabilitation against stroke by regulating epigenetic changes to directly act on its targets, such as the miR-181b/PirB/RhoA/GAP43 axis, which is a novel mechanism of EA therapy." (PMID 27966582, 2016). "Down-regulation of CTGF and RhoA by miR-133b stimulated neurite outgrowth and thereby improved functional recovery after stroke." (PMID 25426026, 2014). "In contrast, treatment of stroke in rats with MSCs containing increased miR-133b, inhibited RhoA expression in neurons which enhanced the regrowth of the corticospinal tract after injury." (PMID 25426026, 2014). "A clinical study showed that statins treatment before stroke could decrease the levels of pro-inflammatory factors after stroke, and RhoA GTPase as well as its downstream effectors might be the targets for statins to exert anti-inflammatory effects." (PMID 38932932, 2024). "Therefore, inhibition of the RhoA-ROCK signaling pathway plays a very important role in the treatment of stroke and has become a potential therapeutic target." (PMID 35889443, 2022). "However, in stroke-prone SHRs, the active form of RhoA and the phosphorylation of MYPT1 at T696 in vascular smooth muscle cells were higher than in WKY rats." (PMID 34357074, 2021). "Moreover, electroacupuncture can enhance rehabilitation against stroke by targeting miR-181b/PirB/ RhoA/GAP43 axis and leading to epigenetic changes." (PMID 30579356, 2018). "The inhibition of the RhoA/ROCK pathway also has neuroprotective effects after stroke." (PMID 25374504, 2014). "In addition, Mir133b may promote neurite outgrowth via targeting RhoA and miR-133b may be critical for neural functional recovery after spinal cord injury and stroke in several organisms." (PMID 32093602, 2020). "In L-NAME-treated hypertensive rats VSM cells, as well as in DOCA–salt rats, renal hypertensive rats and stroke-prone SHR rats, angiotensin II increased the active form of RhoA, phosphorylation of MYPT1 at T696 and CPI-17 T38." (PMID 34357074, 2021). "Several studies have demonstrated the involvement of the RhoA/ROCK pathway in the pathophysiology of neurological disorders such as spinal cord injury (SCI), optic nerve injury, stroke, and inflammatory CNS diseases." (PMID 25374504, 2014).
Stroke (continued). "Evidence from animal studies reveals that RhoA/ROCK signaling is involved in various central nervous system (CNS) diseases, including optic nerve and spinal cord injuries, stroke, and neurodegenerative diseases." (PMID 25374504, 2014). "As peripheral blood markers of the ischemic penumbra, the expression patterns of CDC42 and RHOA in nonhuman primate stroke models differ from those in rats that we previously reported." (PMID 36831829, 2023). "RhoA and ROCK inhibitors appear to be effective in animal models of stroke." (PMID 23687965, 2013). "In the current study, we evaluated whether the levels of CDC42 and RHOA in plasma are related to DWI-FLAIR mismatch in the hyperacute phase of stroke in nonhuman primates." (PMID 36831829, 2023). "In a mouse stroke model, CDC42, not RHOA, was the main protein related to cytoskeleton formation and cell polarization." (PMID 36831829, 2023).
Hyperglycemia (27 papers, 2012 to 2025). An increased concentration of glucose in the blood. "Rutin, a naturally occurring flavonoid substance, was discovered to stop hyperglycemia from causing renal endothelial cell barrier failure by blocking off the ROCK/RhoA signaling pathway." (PMID 36235602, 2022). "Hyperglycemia is a major factor in influencing the patency rate of arteriovenous shunts, potentially associated with the RhoA/Rho-associated protein kinase (ROCK) pathway." (PMID 31080833, 2019). "We supposed that hyperglycemia is associated with AV shunt thrombosis through the RhoA/ROCK pathway, inducing platelet activation." (PMID 31080833, 2019). "The RhoA/ROCK1 signaling pathway is known to play an important role in endothelial cell injury caused by hyperglycemia in vitro." (PMID 29849894, 2018). "SRGAP2a inactivates RhoA/Cdc42 to suppress podocyte motility, maintaining structure and preventing injury under hyperglycemia or TGF-β stimulation." (PMID 41009556, 2025). "Kaempferol inhibits hyperglycemia-induced RhoA activation and diabetic kidney disease by reducing oxidative stress and proinflammatory cytokine levels." (PMID 37242603, 2023). "Studies demonstrated that kaempferol plays vital nephroprotective roles associating with inhibiting oxidative stress, proinflammatory cytokines (TNF-α and IL-1β), and fibrosis in DN via inhibiting hyperglycemia-induced activation RhoA/Rho-kinase." (PMID 34349833, 2021). "The effect of hyperglycemia on miR-133a expression and RhoA/Rho kinase pathway and muscle contraction was reversed by anti-oxidant NAC treatment both in vivo and in vitro." (PMID 28678840, 2017). "Using smooth muscles from the fundus of ob/ob mice and of wild type (WT) mice treated with 30 mM glucose (HG), we identified the molecular mechanism by which hyperglycemia upregulates RhoA/Rho kinase pathway and muscle contraction." (PMID 28678840, 2017). "Similar increases in RhoA expression and Rho kinase activity in response to hyperglycemia in vitro were observed in muscle cells from WT mice treated with HG for 48 h." (PMID 28678840, 2017). "Hyperglycemia has been suggested to stimulate RhoA/ROCK signaling through the generation of reactive oxygen species (ROS)." (PMID 27724862, 2016). "There is strong evidence that hyperglycaemia and or hyperlipidaemia evoke reactive oxygen species to stimulate RhoA/Rho-kinase signalling." (PMID 24059472, 2013). "Our data provides new information related with association between important role of RhoA/ROCK pathway via depressed eNOS due to less endothelial NO-production and impaired mechanical activity of aorta under hyperglycemia." (PMID 23530857, 2013). "Considering the roles of RhoA-mediating signaling in cellular functions as well as regulation of vascular tone along with inflammation, hyperglycemia, and oxidative stress, the inhibition of this pathway seems to have significant clinical implications." (PMID 23530857, 2013). "The ability of hyperglycemia to augment arginase activity likely occurs via the RhoA pathway, which can stimulate the induction or activation of both arginase isoforms." (PMID 23730303, 2013). "Simvastatin prevented high glucose or hyperglycemia-induced dysregulation of occludin and ZO-1 by inhibition of RhoA/ROCK1 signaling in cultured GEnCs and in db/db mice with early-stage DN." (PMID 24244596, 2013). "In addition, hyperglycemia, hyperlipidemia and advanced glycation endproducts activate RhoA/ROCK pathway in endothelial cells and VSMCs." (PMID 35769086, 2022). "The activity of RhoA/Rho kinase signaling pathway was enhanced in microvascular tissue following maternal hyperglycemias, and the inhibition could attenuate acute hypoxic fetoplacental vasoconstriction in rats." (PMID 31017969, 2019). "Collectively, these data indicate that S1PR2 is critical in the remodeling of mitochondrial morphology and mitochondrial functions, and may participate in hyperglycemia-induced dysfunction of HRGECs, possibly by regulating RhoA/ROCK1." (PMID 30999892, 2019).
Hyperglycemia (continued). "Our data indicated that hyperglycemia-induced Rac1 activation could be mediated by mtROS either directly or via stimulation of RhoA that balanced Rac1-dependent cytoskeleton rearrangements." (PMID 28761623, 2017). "Hyperglycemia is thought to activate PKCβ2, which in turn activates iNOS and RhoA/ROCK signaling." (PMID 27724862, 2016). "RhoA and Rho kinase may also be involved in hyperglycemia-induced cell growth and serum response element- (SRE-) dependent c-fos gene expression in rat aortic smooth muscle cells." (PMID 25918730, 2015). "While extensive research showed that RhoA-induced contractile stress fiber formation results in the disruption of the endothelial barrier, only few studies present direct evidence into the role of endothelial stiffening in barrier disruption induced by hyperglycemia, inflammation, and high pressure." (PMID 36714307, 2022). "Thus, the inhibition of mTOR or RhoA/ROCK in glomerular endothelial cells may represent a novel therapeutic strategy for preventing hyperglycemia-induced albuminuria." (PMID 34627341, 2021). "Thus, the effect of NAC in our studies in restoring gastric emptying could be due to its effect on multiple cell types including restoring the effect of hyperglycemia/oxidative stress on RhoA/Rho kinase pathway in smooth muscle." (PMID 28678840, 2017). "Rutin activates Nrf2, reduces reactive oxygen species (ROS), and subsequently inactivates RhoA/ROCK, preventing hyperglycemia-induced hyperpermeability." (PMID 41480358, 2025). "RhoA/ROCK activation has been shown to be involved in the glomerular hyperfiltration of albumin and microvascular/retinal complications of hyperglycemia." (PMID 34627341, 2021). "RhoA/ROCK1 is the key signaling pathway that couples S1PR2 and modulates endothelial cell dysfunction induced by hyperglycemia." (PMID 30999892, 2019). "In kidney of STZ-induced diabetic rats and high glucose-treated mesangial cells, expression of RhoA on the cell membrane is significantly upregulated, and the RhoA/ROCK signaling pathway can also be activated by oxidative stress and hyperglycemia." (PMID 31844679, 2019). "Numerous molecular and cellular studies have demonstrated that small GTP-binding proteins, consisting of the Ras and Rho family (RhoA and Rac1), participate in the VSMC mitogenic machinery triggered by hyperglycemia." (PMID 25918730, 2015). "In ischemic heart disease, RhoA/ROCK inhibitor fasudil induces postconditioning against myocardial infarction via m-KATP channels in the rat; although hyperglycemia attenuates it, high-dose fasudil can restore cardioprotection." (PMID 22694757, 2012).